KLF4 (KLF transcription factor 4)
Diseases named in the same sentence as KLF4 in open-access papers (continued):
Sharing a sentence is not in itself a finding about the gene and the disease.
lung carcinoma (continued). "The clinical and experimental evidence strongly suggest that KLF4 functions as a tumor suppressor gene in human lung cancer and its altered expression plays an important role in lung cancer development and progression via regulating hTERT expression." (PMID 27153563, 2016). "To examine the role of KLF4 in regulating hTERT expression in lung cancer cells, we first detected KLF4 expression in various lung cancer cells at the protein level." (PMID 27153563, 2016). "We also analyzed KLF4 and its relevant factors in lung cancer using a data portal (cBioPortal for Cancer Genomics)." (PMID 27153563, 2016). "Numbl, a polarity protein Numbl, was revealed to suppress the KLF4 ‘stemmness' transcriptaional program, resulting in shortened relapse-free survival in patients with lung cancer." (PMID 27153563, 2016). "KLF4 expression in lung cancer cells inhibited cell growth, and the overexpression of hTERT neutralized the effect of KLF4." (PMID 27153563, 2016). "However, late-stage lung cancer patients showed a marked loss of KLF4 expression (p = 0.0486) and a significant association in the distribution of patients according to metastatic lymph nodes (p = 0.0063), suggesting that the loss of KLF4 expression might contribute to lung cancer progression." (PMID 27153563, 2016). "Taken together, these results demonstrate that KLF4 suppresses lung cancer growth by inhibiting hTERT and MAPK signaling." (PMID 27153563, 2016). "In silico analysis using the cBioPortal for Cancer Genomics showed that the protein KLF4 is deregulated in lung cancer whereas TERT steadily presented amplification." (PMID 27153563, 2016). "Moreover, overexpression of KLF4 in the A549 and H1703 lung cancer cell lines resulted in a decline in cell proliferation as determined by the CCK-8 assay." (PMID 38808570, 2024). "A significant reduction of KLF4 mRNA expression was observed in these two lung cancer cell lines." (PMID 38808570, 2024). "Although stable KLF4 could suppress lung tumorigenesis, the function for lung cancer stem cells is largely unknown." (PMID 39695175, 2024). "Increasing KLF4 could inhibit the cell growth and promote apoptosis of lung cancer, revealing the molecular mechanism of HDACi-induced cell cycle arrest and apoptosis." (PMID 38560274, 2024). "So the KLF4/PLAC8 axis should be a candidate targeted therapy for lung cancer." (PMID 38560274, 2024). "Consistently, KLF4 expression also decreased in lung cancer tissues and cell lines." (PMID 38808570, 2024). "Clinically, KLF4 is significantly lower in lung cancer than in normal lung tissue." (PMID 37031197, 2023). "In contrast, USP10 exerts a tumor suppressor effect by stabilizing KLF4 in lung cancer." (PMID 36526897, 2023). "The anticancer activity of TSA against human lung cancer could be mediated by the upregulation of Krüppel-like factor 4 (klf4) which acts as a tumor-suppressor in the A549 cell line upon TSA treatment." (PMID 36297347, 2022). "Therefore, it is of value to further delineate the exact role of KLF4 on lung cancer pathogenesis and disease progression as well as metastasis." (PMID 33882454, 2021). "Additionally, KLF4 is found to act as important player in the progression of many aggressive cancers, such as lung cancer." (PMID 33596966, 2021). "Furthermore, KLF4 directly bound to the miR-1915 promoter and transcriptionally regulated miR-1915 expression in lung cancer cells." (PMID 34774019, 2021). "We found KLF4 expression were enhanced following METTL3 or YTHDF2 knockdown in lung cancer cells." (PMID 34774019, 2021). "Moreover, studies have found that KLF4 accumulation in the nucleus of lung cancer has a worse prognosis than cytoplasmic accumulation." (PMID 33127882, 2020).
lung carcinoma (continued). "Previous studies found that KLF4 may function as a tumor suppressor gene in lung cancer; however, its role in the metastasis and invasion of lung cancer remains unclear and needs further exploration." (PMID 31969824, 2019). "The expression of KLF4 in lung cancer tissues was further demonstrated using immunohistochemistry." (PMID 31969824, 2019). "However, in a number of cancers, including lung cancer, ovarian cancer and oesophageal squamous cell carcinoma, KLF4 was reported to suppress chemoresistance and enhance cell apoptosis." (PMID 30176890, 2018). "Taken together, restoration of KLF4 expression may produce potential in treating lung cancer in the future." (PMID 27153563, 2016). "Significant variations in KLF4 expression demonstrated that KLF4 might suppress lung cancer cell growth and hTERT expression via MAPK signaling." (PMID 27153563, 2016). "Taken together, these findings indicated that there might be crosstalk between hTERT and KLF4 in lung carcinoma." (PMID 27153563, 2016). "Clinical data revealed the prognostic significance of KLF4 and hTERT expression in lung cancer." (PMID 27153563, 2016). "In addition, the KLF4 and hTERT expression levels were significantly related to the clinicopathological features of lung cancer patients." (PMID 27153563, 2016). "Moreover, hTERT overexpression can partially rescue the KLF4-mediated suppressive effect in lung cancer cells." (PMID 27153563, 2016). "The results showed that a crosstalk between TERT and KLF4 existed in lung carcinoma." (PMID 27153563, 2016). "Thus, KLF4 and hTERT can be used as novel biomarkers for predicting the outcomes of lung cancer patients." (PMID 27153563, 2016). "Previously, we showed that KLF4 functions as a tumor suppressor in primary lung cancer." (PMID 27153563, 2016). "Additionally, the KLF4/hTERT/MAPK pathway is a potential new therapeutic target for human lung cancer." (PMID 27153563, 2016). "KLF4 also has an important function in the development of primary lung cancer." (PMID 23861801, 2013). "Oncogenic effects of KLF4 have been reported in breast, skin, and lung cancers." (PMID 23006636, 2012). "Similarly, in lung cancer cells, KLF4 is also considered to possess tumor‐suppressive capabilities." (PMID 41532367, 2026). "Similarly, polarity protein NUMBL expressed in normal neural progenitor cells maintains progenitor-like characteristics in lung cancer by inhibiting KLF4, and restores KLF4 expression level can destroy progenitor cell subsets, thereby inhibiting the growth of lung cancer cells." (PMID 39695175, 2024). "Moreover, the depletion of KLF4 facilitates the development of lung cancer." (PMID 35627217, 2022). "Furthermore, decreased KLF4 promoted lung cancer cell viability, adhesion, migration and cancer formation, while hTERT could partially rescue the suppressive function of KLF4 in cell proliferation." (PMID 27153563, 2016). "Thus, we hypothesize that KLF4 may play an important role in regulating telomerase activation and hTERT expression in lung carcinoma." (PMID 27153563, 2016). "In non‐small cell lung cancer (NSCLC), higher KLF4 levels are observed in stages II, III, and IV compared to stage I. Intriguingly, some studies suggest a tumor suppressor‐like role for KLF4 in specific cancers." (PMID 40755294, 2025). "In this paper, KLFs have been summarized via systematic reviews, with either a promoting (KLF4 ∼ KLF8, KLF15) or an inhibiting (KLF2 ∼ KLF6, KLK9 ∼ KLF12 and KLF17) roles, which should be useful to monitor lung cancer progression or understand its mechanisms." (PMID 38560274, 2024).
lung carcinoma (continued). "Next, we measured the expression of KLF4 in human normal lung bronchial cell line BEAS-2B and lung cancer cell lines A549 and H1703." (PMID 38808570, 2024). "Among the KLFs, the clear promoting effects on lung cancer were KLF5, KLF7, KLF8, and KLF15, as well as KLF4 and KLF6, which have dual functions." (PMID 38560274, 2024). "In fact, KLF4 inhibited the growth, migration, invasion, metastasis and EMT of lung cancer cells through SIRT6/Snails/KLF4, KLF4/Plac8, Numblike-KLF4, KLF4-MMP2 and c-Jun-NH2-terminal kinase signaling pathway." (PMID 37031197, 2023). "A study has shown that TRHDE-AS1 is a low-expression gene in lung cancer and overexpression of TRHDE-AS1 affects the cell growth through the miRNA-103/KLF4 axis." (PMID 37101543, 2023). "KLF4 downregulation activates hTERT and telomerase activity, MAPK signaling, and thus lung cancer cell growth." (PMID 36661515, 2023). "Another supporting study showed that TRPM7 overexpression resulted in the increased expression of cancer stemness markers such as SOX2, KLF4, and CD133 in lung cancer, while TRPM7-silencing led to the reduction of stemness and EMT traits." (PMID 35771152, 2022). "In numerous clinical studies, overexpression of KLF4 inhibited cell growth, migration, invasion and metastasis in HCC, lung cancer and CRC and induced tumour cell apoptosis in oesophageal cancer and bladder cancer." (PMID 35177016, 2022). "Through deubiquitinating transcription of KLF4, ATXN3 is responsible for inducing lung cancer development." (PMID 33613103, 2021). "KLF4, a member of SP/KLF transcription factor family, was reported to be down-regulated in gastric, colon, breast, lung cancers, and repress tumor proliferation and migration." (PMID 34249701, 2021). "The underlying molecular mechanism is analogous to that employed by MALAT1 in NSCLC (Section 5: Lung cancer): SNHG5 directly binds miR-32 and in this way it reduces the inhibitory effects of miR-32 on KLF4 activity." (PMID 33266506, 2020). "However, the role of KLF4 in lung cancer metastasis remains unclear." (PMID 31969824, 2019). "KLF4 is downregulated also in lung cancer compared to nontumor tissues, presenting the characteristics of tumor suppressor." (PMID 39135777, 2024). "According to the TRN of lung cancer, SOX4, FOXM1, ETV4, HOXC6, and E2F3 are the main positive regulators, whereas SOX17, KLF4, and ZBTB16 are the main negative regulators of transcription, controlling the expression of other TFs and target genes in lung cancer." (PMID 39228892, 2024). "As previous research showed that in bladder cancer METTL3/YTHDF2 m6A axis accelerates carcinogenesis by degrading transcription factor KLF4, we also examined whether METTL3/YTHDF2 m6A axis inhibited KLF4 expression in lung cancer." (PMID 34774019, 2021). "And the interaction of ITGB4 promoter with some transcription factors in other disease is also reported, such as KLF4 in glioma 21, RUNX1 in myeloid leukemia 22, ZEB1 in prostate cancer 23, TP73 in lung cancer 24, GLI1 in ovarian cancer 25, and JUN in pancreatic cancer." (PMID 31602273, 2019). "To test whether MACC1 regulate KLF4 via miR-25 and to determine whether the reduced expression of miR-25 was responsible for MACC1 silence mediated stabilization of KLF4 mRNA, we performed rescue experiments by transfecting miR-25 mimics in MACC1 stably knockdown in lung cancer cells." (PMID 39695175, 2024). "Additionally, HMGA2 and KLF4 regulation are able to promote PI3K/Akt phosphorylation, resulting in increased drug resistance, and miR-26a interacts with HMGA2 and miR-145 with KLF4 to promote DDP-resistance in lung cancer cells." (PMID 35444536, 2022).
lung carcinoma (continued). "CHIP assays using KLF4 antibody showed enrichment of miR-1915 promoter in A549 and H1975 cells, whereas negative control (IgG and Ab- groups) did not, demonstrating that KLF4 directly bound to the miR-1915 promoter in lung cancer cells and transcriptionally regulated miR-1915 expression." (PMID 34774019, 2021). "Hence, we speculate that KLF4 may serve as a downstream regulatory target of MACC1 mediated non-CSCs dedifferentiation in lung cancer." (PMID 39695175, 2024). "High-throughput sequencing and tumor specimen analysis revealed that MACC1 was negative correlated with Krüppel-like factor 4 (KLF4) expression level, which acts as a negative stemness regulator in lung cancer." (PMID 39695175, 2024). "Therefore, KLF4 can be used as a negative regulator of cancer stem cells in lung cancer, and it is also consistent with the result of knocking down MACC1 to inhibit the dedifferentiation of non-CSCs in lung cancer by up-regulating the expression of KLF4." (PMID 39695175, 2024).
gastric cancer (76 papers, 2006 to 2026). A primary or metastatic malignant neoplasm involving the stomach. "Taken together, the KLF4 expression level appears to be associated with the TRAIL susceptibility of gastric cancer cells." (PMID 36661504, 2022). "Expression of OCT4, SOX2, and Nanog, either alone or in combination was found positively associated with phenotypes of advanced gastric cancer and worse prognosis, while that of KLF4 was inversely correlated." (PMID 36661504, 2022). "To demonstrate the underlying mechanism of miR-103’s action in gastric cancer, we confirmed Krüppel-like Factor-4 (KLF4) as a direct target of miR-103." (PMID 28445396, 2017). "Previous study also reported that KLF4 was a proliferation- and metastasis-associated gene in gastric cancer." (PMID 28445396, 2017). "In a subset of human gastric cancer, the expression of KLF4 is negatively associated with MUC2 expression." (PMID 27277677, 2016). "The KLF4 gene was shown to be genetically and epigenetically inactivated in human pancreatic cancer and gastric cancer, as well as in medulloblastoma, and to be mutated in colon cancer." (PMID 24551169, 2014). "Kruppel-like factor 4 (KLF4) is an underlying tumor suppressor in gastric carcinoma." (PMID 35795038, 2022). "Low KLF4 expression is negatively associated with overall survival rate in gastric cancer patients and may thus serve as a prognostic marker in this type of cancer." (PMID 33266506, 2020). "Loss of KLF4 expression was significantly associated with poor survival in gastric cancer." (PMID 27713138, 2017). "In gastric cancer, loss of KLF4 expression in primary tumors is associated with poor survival." (PMID 20119532, 2009). "Furthermore, loss of KLF4 induces resistance to cisplatin in H. pylori-positive gastric cancer." (PMID 33266506, 2020). "Krüppel‐like factor 4 (KLF4) has a tumor suppressor role in the progression of gastric cancer (GC), and inhibition or loss of KLF4 expression was identified in GC." (PMID 32017451, 2020). "These complex regulatory mechanisms highlight the multifaceted role of KLF4 in gastric cancer biology." (PMID 39995670, 2025). "This study investigates the mechanism by which Krüppel-like Factor 4 (KLF4) suppresses epithelial-mesenchymal transition (EMT) in gastric cancer cells." (PMID 41883394, 2025). "Using Western blot (WB) and reverse transcription-quantitative PCR (RT-qPCR), we evaluated KLF4 protein and mRNA expression levels across gastric cancer cell lines with varying degrees of differentiation." (PMID 41883394, 2025). "In contrast, the long, non-coding RNA SNHG5 positively regulates KLF4 expression and promotes gastric cancer development." (PMID 39995670, 2025). "Results demonstrated that KLF4 overexpression inhibits EMT in gastric cancer cells through the Wnt/β-catenin signaling pathway." (PMID 41883394, 2025). "KLF4 plays a crucial role in the development and progression of gastric cancer and its expression is influenced by multiple regulatory factors." (PMID 39995670, 2025). "miR-135-5b binds to the 3’ UTR of the Klf4 gene, leading to reduced Klf4 expression and promoting the development of gastric cancer." (PMID 39995670, 2025). "Exosome-derived lncRNA HCG18 can up-regulate the expression of KLF4 and promote the polarization of M2 macrophages by sponging miR-875-3p in macrophages, thus regulating the progression of gastric cancer." (PMID 38627703, 2024). "The promoter region of the CXC ligand-8 (CXCL8) gene contains KLF4 binding sites, and the inactivation of KLF4 in gastric cancer tissues resulted in significant upregulation of the CXCL8 expression." (PMID 36761967, 2023). "For instance, in gastric cancer, miR-103 promotes proliferation and metastasis by targeting KLF4, while in endothelial maladaptation, it ameliorates the condition by targeting lncWDR59." (PMID 37894995, 2023).